IL1B (interleukin 1 beta)
Diseases named in the same sentence as IL1B in open-access papers (continued):
Sharing a sentence is not in itself a finding about the gene and the disease.
infection (continued). "Abnormal IL-1β release or lack of IL-1β expression changes the conditions towards a pathological microenvironment, resulting either in chronic inflammation or in the absence of a proper immune surveillance against infections, respectively." (PMID 23935506, 2013). "Surprisingly, neither il1b nor tnfb expression was induced at any level of infection." (PMID 23720235, 2013). "Late il-1β expression in lethally infected mice correlated with an early higher expression of caspase 1 and caspase 4 (also known as caspase 11) on day 3 p.i. compared to nonlethal infection." (PMID 23526993, 2013). "Besides, both IL-1β and MIP-2 are capable of attracting neutrophils to the site of infection." (PMID 24223208, 2013). "In our study, the level of cytokine IL-1β upregulated during initial infection by PRRSV which may contribute to an enhanced virus level in the serum, because IL-1β has a minor effect on the length of virus replication, directly or indirectly, after PRRSV infection." (PMID 23825597, 2013). "Moreover, infection with ΔsseL mutant bacteria did not cause macrophages to secrete more TNF-α (at 10 h post-uptake) and Il-1β (at 24 h post-uptake) when compared to macrophages infected with the wt strain." (PMID 23308136, 2013). "In another study, infection with MDV JM-16 strain could not induce IL-1β expression in the spleen but RK-1 strain led to induction of IL-1β at 4 dpi in both N2a and P2a chicken lines." (PMID 24358317, 2013). "Our findings indicate that compensation of IL-1β in mice lacking the NLRP3 inflammasome may promote the clearance of C. rodentium by stimulating inflammatory macrophages in the early stages of infection." (PMID 24312491, 2013). "Importantly, our findings show that in the absence of PB1-F2 expression, IAV does not induce robust acute IL-1β production and the initial exuberant cellular response to infection is diminished." (PMID 23737748, 2013). "Notably, we observed the enhancement of IL-1β release after infection with a T3SS1 mutant expressing TdhA and S (ΔvcrD1), compared with that after infection with WT bacteria, raising the possibility that T3SS1 is involved in the inhibitory function in addition to triggering caspase-1 activation." (PMID 23357873, 2013). "In addition, transcriptional analysis of inflammatory factors in animals receiving a trickle infection for a long period of time, shows that IL-8 was significantly upregulated at 60 dpe and 60 dpi, whereas COX-2, IL1B and TNFA were only significantly upregulated in the 60 dpi group." (PMID 24330735, 2013). "As in our previous studies, neither P. gingivalis infection alone nor infection combined with 100 μM ATP treatment could induce IL-1β secretion by HIGK cells." (PMID 23936165, 2013). "Interestingly, the IL-6 and IL-1β expression in CEH without trypsin after infection were far lower compared to expression observed with trypsin." (PMID 24252391, 2013). "Interestingly, the viral suppression we observed occurred between 24 and 48 hrs of treatment suggesting that IL-1β signals a response in neurons that restricts virus amplification rather than initial infection." (PMID 23209411, 2012). "IL-1β, which in humans is increased in the first 18 hours of infection, was also markedly increased in brain homogenates, but not in blood in our mice 30 hours after infection." (PMID 22455545, 2012). "IL-1β and IL-8 were downregulated 4 days post infection and remained low in the absence of Vpr." (PMID 22727020, 2012). "We observed that IL-1β was barely detected and not induced during H1N1pdm infection." (PMID 22279582, 2012). "Moreover, we showed that infection of a macrophage cell line with a P. aeruginosa a ΔPopB or ΔS/ΔPopB mutant failed to induce IL-1β maturation, which points to a role for PopB in this process." (PMID 22844497, 2012). "However, these cells clearly were responding to the infection, as Ccl2, Ccl3, and Il1β were upregulated in expression compared to cells from non-infected mice." (PMID 23248776, 2012).
infection (continued). "Absence of Vpr downregulated several proinflammatory molecules such as IL-1α, IL-1β, IL-8 compared to HIV-1wt-infected culture in infection phase, suggest that Vpr could have a specific effect in activating proinflammatory factors, either directly or through enhanced viral replication." (PMID 22727020, 2012). "IL-1β was not induced in response to the pH1N1 infection, which could be explained by our data indicating that its induction was in fact efficiently suppressed by JNK1/2 in swine macrophages." (PMID 22279582, 2012). "From these results we conclude that RIP1 is not required for YopJKIM-induced cell death or IL-1β secretion, however it may enhance IL-1β secretion at early infection times." (PMID 22563435, 2012). "Furthermore, Il1r1−/− BMDCs did not demonstrate any defect in IL-1β secretion after 24 h of infection with Mtb, since in wild-type and knock-out BMDCs about 4ng/ml of IL-1β were secreted." (PMID 22911706, 2012). "FV3 infections of adult frogs elicited rapid increases in the gene expression of pro-inflammatory cytokines such as tumor necrosis factor alpha (TNF-α) and interleukin-1β (IL-1β), which are known to target macrophage lineage cells and orchestrate robust innate immune processes." (PMID 22852041, 2012). "While IL-17R KO animals predictably had significantly higher amounts of IL-17 in brain abscess homogenates, several other mediators were also elevated between 7 and 14 days after infection, including IL-1α, IL-1β, IL-6, CCL3 and CXCL1 (data not shown), as well as CXCL2 and CXCL9." (PMID 22704602, 2012). "Together, these data demonstrate that IL-1β expression but not IL-1α expression is associated with WNV infection in humans and indicates that WNV infection triggers the inflammasome signaling pathway to induce IL-1β during infection." (PMID 23209411, 2012). "Similarly, in vivo infection with IAV resulted in higher levels of primarily neutrophil attracting chemokines such as KC and MIP-2 and several proinflammatory cytokines such as IL-6, TNF and IL-1β in the lungs of A20myel-KO mice compared to wild type mice." (PMID 22396652, 2012). "IL-1β release was significantly reduced at 8 hr, but not at 24 hr post infection with KIM5." (PMID 22563435, 2012). "We therefore first determined the levels of a panel of markers (IL-1β, IL-6, IL-8, IL-10, IL-12p70, TNF, RANTES, MIG, MCP-1, IP-10, IFN-α, IFN-γ, Ang-1, Ang-2, uPAR and VEGF R1/Flt1) in the plasmas of 79 women who remained infection-free from inclusion through to delivery." (PMID 23155405, 2012). "Treatment with necrostatin did inhibit IL-1β release at 8 hours post infection, which may due to lack of interaction between RIP1 and the NF-κB pathway." (PMID 22563435, 2012). "However, 24 h after infection of a macrophage-like cell line (THP-1) or BMDCs with the galU mutant, the amount of IL-1β released into culture supernatants was significantly higher (p < 0.0001 and p < 0.01, respectively) than was observed following infection with WT FT." (PMID 21819572, 2011). "In addition, there was a tendency for the Indo-Oceanic ZERO spoligotype to induce less TNF-α and IL-1β than the EA14_VNM spoligotype after 24 and 48 hours of infection, although these differences did not achieve statistical significance (p>0.05)." (PMID 21931620, 2011). "Interestingly, 24 h post infection, while the sipB mutant still behaved similarly to the ΔSPI1 mutant, the hilA mutant no longer stimulated the expression of IL-1β, IL-8, IL-12β or IL-23α more than did the wild-type S. Enteritidis." (PMID 21314975, 2011). "The peak concentration of IL-1β in the milk at 12 h PC was lower in quarters where infection persisted (0.45 ng/mL, SE 0.23) than in quarters with spontaneously eliminated infections (0.61 ng/mL, SE 0.33), but the difference was not statistically significant (p = 0.44)." (PMID 21414189, 2011).
infection (continued). "Furthermore, cytokine analysis showed that the IFN-γR−/− mice had significantly reduced levels of pro-inflammatory (IL-1α, IL-1β, and IL-6), IL-12p40, IL-17, and chemokine (G-CSF and CXCL1) production compared to WT mice during infection with C. neoformans strain H99γ." (PMID 21359196, 2011). "Unlike the live infections, however, lipids failed to induce IL-1β from macrophages." (PMID 21931620, 2011). "Additionally, we show that infected Dectin-1−/− corneas have impaired IL-1β and CXCL1/KC production, resulting in diminished cellular infiltration and fungal clearance compared with control mice, especially during infection with clinical isolates expressing high β-glucan." (PMID 20617171, 2010). "Since IL-1β may induce IL-6 production by ECs, it is not clear whether IL-6 production by infected cells is a direct result of the infection or is induced by the IL-1β produced in response to infection." (PMID 20824217, 2010). "These included chemokine ligand IP-10 and genes controlled by pro-inflammatory cytokines TNF-α, IL-1β, IFN-γ; namely, interferon regulatory factor 1, Cd274 antigen, metallothionein 2, proteasome subunit (Psmb9), and tumor necrosis factor Tnfsf10 were progressively up-regulated after infection." (PMID 20082697, 2010). "The protein expression levels of MIP-2 and KC decreased significantly (p=0.000) one and three days post-infection in the IL-1β treated group compared to the infected group, but five and seven days post-infection, the expression of MIP-2 and KC was not significantly different (p>0.05)." (PMID 19590756, 2009). "Finally, in the late phase of infection, the level of IL-1β was significantly lower in NLRP3-deficient mouse in comparison with wild type mice and was not detectable in IL-1β-deficient mouse (data not shown)." (PMID 19696895, 2009). "Therefore, it is likely that IL-1β is regulated differently in mice that lack selectin molecules, and that these differences are not due to infection." (PMID 16207337, 2005). "Additionally, the MNoV_S99 infection did not significantly alter the transcription of Il1b." (PMID 40395509, 2025). "Furthermore, we observed that pro-inflammatory mediators including IFN-α, IL-1β, IL-16, NF-κB, and TNF-α exhibited similar dynamic patterns, with their expression levels progressively increasing during early infection, peaking at 36 h, and subsequently declining with prolonged infection time." (PMID 41305370, 2025). "The differential expression of SAA, IL-1β, and IL-6 was statistically nonsignificant at most time points following Ich infection, suggesting that these molecules may primarily be activated during the acute phase of infection." (PMID 40509043, 2025). "Research has shown that inflammatory factors such as IL-1β, IL-6, IL-8, and TNF-α can induce and recruit various types of white blood cells to participate in immune responses, which may lead to tissue damage and affect the healing of infections if present long-term." (PMID 40529353, 2025). "Of note, infection with rCDC-9 P11 VP4_AA385 did not downregulate the pro-inflammatory response for selected cytokines (e.g., IL-1β, IL-18 MIP-1α) indicating that AA385 might be involved in reduced viral shedding in vivo but did not modulate inflammatory responses as seen with rCDC-9 P11 VP4_AA331." (PMID 41060027, 2025). "Additionally, there was no significant change in IL-1β levels between PmCQ2 and Δfis infection." (PMID 40329318, 2025). "However, blockade of IL-1β does not improve infection outcomes." (PMID 39541407, 2024). "However, although IL-1β increased pig immune responses, it did not protect pigs against infection." (PMID 39024231, 2024).
infection (continued). "Additionally, a significant age-related increase in human and rhesus monkey plasma IL-6 and IL-1β, even in the absence of inflammation or infection, indicates that proinflammatory cytokines IL-6 and IL-1β are important mediators of the age-associated increase in intestinal permeability." (PMID 38785555, 2024). "For example, inflammatory cytokines such as IL-1β are not significantly increased within 96 h after infection and show no significant increase in the serum from asymptomatic and mild patients in the early stages of the disease, but they are significantly increased in the late stage of infection." (PMID 38004809, 2023). "Similarly, low production of virions from reactivated reservoir cells could result in abortive infection in presence of ART, leading to activation of inflammasome and proinflammatory caspases responsible for release of proinflammatory cytokines (IL-1β and IL-18)." (PMID 37953818, 2023). "We first assessed whether the BV2 cells were effectively activated by quantifying the mRNA levels of IL-1β, a representative indicator of BV2 cell activation, and measured the levels of IL-1β in cell culture supernatants of the group before and after transfection and before and after infection." (PMID 37894158, 2023). "Furthermore, we found that IL-1β was also not induced after infection with wild-type M. ulcerans." (PMID 37910490, 2023). "Furthermore, we did not detect a significant change in IL-12 or IL-1β during infection." (PMID 37862368, 2023). "Indeed, we observed that the most considerable augmentation of pro-inflammatory IL-1β, IL-6, IL-15, IL-18, IFN-γ, eotaxin, GRO-α, IP-10, MCP-1, MIP-1α, MIP-1β, and regulatory IL-1RA, occurred at the terminal stage of the disease (7 days post-infection) in our rhesus macaques." (PMID 38035334, 2023). "However, the protein secretion of IL-1β during infection with non-cytopathic biotype strains is lower than that with cytopathic strains; this could be related to the processing of IL-1β by inflammasomes." (PMID 37515181, 2023). "However, this high and long-term induction of IL-1β is not sufficient to warrant infection control, suggesting that the self-regulation of the immune response may be abrogated leading to a constant activation of IL-1β expression." (PMID 37155695, 2023). "However, although caspase-8 was cleaved in TNF/SM treated macrophages and neutrophils, caspase-8 was not cleaved following PAO1 infection, indicating that there is no requirement for caspase-8 in GSDMD processing or IL-1β secretion induced by PAO1 infection of neutrophils." (PMID 37730693, 2023). "In addition, the same was held with SVCV infection, we found that bazedoxifene/Stattic/17-AAG/AUY922/PGE2/VPA treatment inhibits or increases the SVCV genome entry, and the transcription of pro-inflammatory cytokines (IL6, TNF-α, IL1β) accordingly in a dose-dependent manner." (PMID 37099596, 2023). "In addition, we also found that the mRNA transcript levels of pro-inflammatory cytokines IL-1β, TNF-α, IL-6, and IL-12, and anti-inflammatory cytokines IL-4, and IL-10 tended to decrease (p < 0.05 or p < 0.01) in the cats from the feIFN-ω’ treatment group, compared with the FPV infection group." (PMID 35068319, 2022). "However, we did not observe a strong difference between steady-state levels of other ARE-containing cytokine transcripts (VEGF, IL-1β, and GM-CSF) after WT versus ΔKapB infection, since not all ARE-RNAs respond in the same manner to altered PB dynamics, as shown in a previous study." (PMID 34936820, 2022). "However, when acetate was included in the Hi2019WT infection assay, an anti-inflammatory effect was observed that resulted in a 47% (2-Way ANOVA, p = 0.0021) and 26% (2-Way ANOVA, p = 0.0001) reduction of IL-6 and IL-8 expression, while IL-1β expression was essentially unchanged." (PMID 35085362, 2022).
infection (continued). "Importantly, single-round infections with all viruses were much less sensitive to IL-1β and IFN treatment when added, for example, 6 h post infection, consistent with a model in which single-round infections induce cytokines too late to inhibit that first round of infection." (PMID 36289397, 2022). "Bannerman found a significant increase in IL-1β levels in milk after S. aureus infection, while TNF-α levels did not change, so the authors suggested that the limited cytokine response to S. aureus may contribute to the well-known ability of the bacterium to establish chronic intramammary infection." (PMID 35624447, 2022). "In conclusion, infection of porcine blood ex vivo with S. suis wt and 10ΔdltA indicates that d-alanylation of LTAs results in increased secretion of IL-1β, while the level of alanylation of purified LTAs, used for ex vivo stimulation of porcine blood, did not influence the amount of secreted IL-1β." (PMID 35509315, 2022). "We had shown previously that fibroblasts from other skin areas showed increased expression of IL-1β mRNA in response to stimulation with heat-inactivated D. nodosus, demonstrating those bacteria can elicit a pro-inflammatory response in the absence of active infection." (PMID 36496756, 2022). "Moreover, il-1b mRNA transcripts were significantly upregulated in response to S. enterica LPS and YopJC172A Y. pseudotuberculosis but not to wild-type Y. pseudotuberculosis infection." (PMID 34319170, 2021). "Our result indicated that although anti-IL-1β therapy (0.2μg/g) could extend the time it took for the animal’s body temperature to rise to 42 °C (132.04 ± 11.32 min vs 120.00 ± 15.03 min) without prior infection, the difference was not significant (p = 0.2)." (PMID 34092247, 2021). "Remarkably, we found higher TNF, IL-1β, IL-6, and IL-10 in lung homogenates of LysM-cre × Hif1αfl/fl mice when compared with Hif1αfl/fl control mice at 12 hours after inoculation, but these differences in pulmonary cytokine levels were not present after 40 hours of infection." (PMID 34393650, 2021). "However, it is most likely the release of IL-1β, rather than IL-1α, associated with chemokine induction and neutrophil recruitment during GAS or S. aureus infection, as previously reported in other infection models involving bacterial pathogens." (PMID 33525468, 2021). "Thus, it is logical to speculate that in the absence of GSDMD, either a decrease in IL-1β mediated weak protection or an increase in Cxcl1 exacerbated infection." (PMID 34011393, 2021). "By acting as a possible counterregulator of pro-IL-1β production, we hypothesized that these rickettsial species would trigger differential levels of type I IFNs in THP-1 macrophages, as evidenced by the observed differences in the abundance of several ISGs between infection conditions." (PMID 34935429, 2021). "This set of data indicates that the T4SS might contribute to the release of inflammatory cytokines immediately post-infection in moDCs, whereas it does not play a crucial role in the secretion of IL-1β, IL-8, and TNFα and in surface marker expression at later time points." (PMID 32486097, 2020). "Importantly, in contrast to previous IAV/bacteria associations studied in the past, e.g., IAV/S.aureus; IAV/ S. pneumoniae, IAV pre-treatment did not condition the host to further PAO1 infection by restraining the IL-1β-IL-17 pathway, and/or neutrophilic responses to bacteria." (PMID 32117268, 2020). "We did not observe decreased IL-1β 16 h post-infection, but this difference might be explained by the different durations of infection, or it could be a consequence of species-specific differences in DC function, which furthers emphasizes the advantage of using human cDC2s." (PMID 32486097, 2020).